LEF1 (lymphoid enhancer binding factor 1)
Diseases named in the same sentence as LEF1 in open-access papers (continued):
Sharing a sentence is not in itself a finding about the gene and the disease.
cancer (continued). "Overall, this literature suggests that the Wnt/β-catenin/Lef1 pathway may contribute to both the regulation of uterine growth (at least in the context of cancer), and normal development and function of the uterus." (PMID 22792274, 2012). "Finally, we investigated the roles of cyclin D1 and MMP7 in gland and cancer formation in the mouse, and assessed the relevance of Lef1 to human cancer by comparing expression levels in cancerous and normal endometrial tissues." (PMID 22792274, 2012). "Consequently, targeting LEF1 appears to be beneficial in suppressing cancer proliferation." (PMID 39820173, 2025). "Our observation of a reduction in the number of p40‐positive cancer cells upon LEF1 suppression in exp‐CAF 544 cells suggests that LEF1 expression in the exp‐CAFs may contribute to SCC characteristics in DCIS.com cells coimplanted with them in our xenograft system." (PMID 39887653, 2025). "Therefore, detecting the level of phase separation in LEF1 may be an effective method for predicting cancer proliferation and metastasis." (PMID 37657935, 2023). "We selected CDH3, LEF1, and MMP7 as candidate biomarkers to construct a back propagation neural network model from hub genes, which may be helpful for the early diagnosis of cancer through the high-risk early warning range." (PMID 34485109, 2021). "Furthermore, we performed a β-catenin/TCF4 binding promoter luciferase activity assay-based high throughput screening using a natural products library, containing 502 single compounds isolated from Chinese herbs, to find an inhibitor of β-catenin/TCF4/LEF1-mediated cancer growth and progression." (PMID 32933177, 2020). "Furthermore, a significant association was observed between overexpressed LEF1 and poor OS in Chinese cancer patients (HR = 1.88, 95% CI: 1.04–3.39, P=0.036), but not in Caucasian cancer patients (P=0.263)." (PMID 32856045, 2020). "Thus, LEF1 is a promising molecular target for cancer treatment." (PMID 32933177, 2020). "From statistical analysis, we identified Lef1, a transcription factor in the Wnt-signaling pathway, whose expression level in most the cancerous lesions was well above the level found in the adjacent normal tissues, as well as the level found in the gastric tissues of other non-cancer patients." (PMID 32824603, 2020). "Thus, LEF1 is considered a potential therapeutic target for cancer treatment." (PMID 32933177, 2020). "Moreover, gene ontology (GO) analysis revealed that the overexpression of LEF1 significantly affected the positive regulation of mesenchymal cell proliferation, which might be the reason for the development of cancer stem cells." (PMID 31296250, 2019). "For example, as Lef1 is upregulated at the invasive fronts of both lung and colorectal invasive cancers and canonical Wnt signaling via Lef1 is active in the leading region of the pLLP we can use the leading region of the pLLP as a model for collective cancer invasion." (PMID 30175096, 2018). "In complex with FHL2 (four- and one-half LIM domains protein 2), β-catenin, and Lef-1 (lymphoid enhancer-binding factor-1), EpICD has been shown to induce the transcription of specific oncogenes, such as cyclins and c-myc, thereby promoting cancer cell proliferation." (PMID 23667256, 2013). "Inhibition of LEF1 expression with sodium selenite, Paclitaxel (PTX), 5-aza-2’-deoxycytidine and ethacrynic acid (EA) has provided potential therapy for cancer treatment." (PMID 39820173, 2025). "Future research should further explore the interactions between LEF1 and other TME factors to understand its universal role in various cancers, thereby driving the development of next-generation cancer therapies." (PMID 40810004, 2025). "Overall, our study highlights that in CRC, the TGF-β signaling pathway can elevate LEF1 transcriptional activity, promoting the EMT process in cancer cells." (PMID 40810004, 2025).
cancer (continued). "Injury-induced populations were highest for TFs related to cell proliferation, self-renewal, and cancer involving both intrinsic (E2F family, MYC, and ZFX) and extrinsic (HIF1a, EPAS1/HIF2a, NFYB, LEF1, GLI2, VDR, and SMAD1/3/5) pathways." (PMID 38905342, 2024). "LEF1, WT1 and BCL11B copy number abnormalities were reported from the TARGET study of 2471 pediatric cancer patients whereas in our group we found CDKN2A, CDKN2B and MTAP harboring most copy number variations." (PMID 38459434, 2024). "In cancer, an upregulation of WNT signaling has been observed, which promotes the WNT downstream protein β-catenin and its binding to lymphoid enhancer-binding factor 1 (LEF1) in the nucleus." (PMID 38473318, 2024). "The transcription factor LEF1 belongs to the T-cell factor (TCF)/LEF family and is known for its role in cancer cell migration, invasion, proliferation, and viability." (PMID 37553362, 2023). "It has been reported that NELFB has a synergistic effect with TCF1 in T cell response to cancer, while a non-coding RNA AK045490 inhibits osteogenic differentiation by down-regulating the expression of TCF1, LEF1 and Runx2." (PMID 38260098, 2023). "We found that the significantly activated regulons were involved in T cell biology (RORC, TCF7, NFATC1, and LEF1) or disease pathogenesis (IKZF2 for CD30+ TMF and BATF3 for cALCL) or reported cancer biology (POUZAF1 and TSHZ2)." (PMID 37790936, 2023). "To detect the logarithm fold change (logFC) in the expression of the four genes TCF7, LEF1, CD8A, and CD8B in different cancers, we investigated the transcriptomic profiles retrieved from the TCGA database." (PMID 35588138, 2022). "During cancer metastasis it is extensively accumulated in the cytoplasm and transported to the nucleus to act as co-activator of TCF/LEF-1 signalling pathway." (PMID 35683030, 2022). "Further, we measured the protein levels of cancer cell metastasis-related markers (E-cadherin and vimentin) and the genes of interest (MEF2A and LEF1) were measured." (PMID 34957213, 2021). "Membrane EpCAM is cleaved in cancers and its intracellular domain (EpICD) is transported into the nucleus and binds β-catenin, FHL2, and LEF1." (PMID 34209658, 2021). "Mechanistically, LSD1 complexes with β-catenin to transcriptionally upregulate LEF1 and subsequently enhances EMT-mediated cancer progression." (PMID 32850370, 2020). "Among them were five genes with known transcription factor activity (PBX3, HOXB3, LEF1, HOXA7, LBH) and three genes with oncogenic potential (PAPD7, PBX3, LEF1) for which a role in other cancers has been suggested previously." (PMID 32728112, 2020). "Increasing evidence has shown that LEF1, which belongs to the T cell factor (TCF) family, acts as a cancer-promoting transcription factor by cooperating with the canonical Wnt/β-catenin signaling pathway." (PMID 32933177, 2020). "Among the pathways known to regulate the self-renewal properties of cancer cells, the TGF-β signaling pathway was significantly dysregulated in LEF1-overexpressing ECA109 cells." (PMID 31296250, 2019). "LEF1 is also a facilitator of epithelial-mesenchymal transition (EMT), a feature of cancer cell migration and invasion, as well as cancer cell proliferation and viability." (PMID 31296250, 2019). "Hallmark capabilities enabled by epithelial-mesenchymal transition include sustained proliferation, with cell cycle components controlled by SP1, LEF1, and FOXO4 up-regulated in cancer cell lines." (PMID 28798381, 2017). "By interaction with downstream transcription factors, such as TCF4 or Lef-1, the β-catenin/Lef/TCF complex was formed which impacts the transcription activity of multiple genes that are involved in cancer survival, metastasis, and apoptosis." (PMID 27801803, 2016). "Among these 10 hubs are 5 – ACP1, HSP90AA1, LEF1, MLH1, and RBM5 - common to the major identified cancer-related pathways." (PMID 27809917, 2016).
cancer (continued). "SNAI1 has also been reported to increase the expression of mesenchymal markers Vimentin and Fibronectin as well as other proteins involved in cancer invasion such as metalloproteinases 2 and 9, and various transcription factors such as ZEB-1 and LEF-1." (PMID 24565133, 2014). "Several studies have shown elevated levels of LEF-1 in human cancers, in particular in chronic lymphatic leukemia (CLL) and a very recent study describes an alteration in LEF-1 mRNA and protein expression in a wide cohort of DLBCLs." (PMID 23650540, 2013). "For the nine added TF genes, seven of them were reported to take part in apoptosis in various types of cancer or diseases; these seven TFs are STAT3, ETS1, LEF1, STAT4, E2F3, ATF3, and HMGA2, which have not been annotated by GO yet." (PMID 22952919, 2012). "To this end, we analyzed by immunofluorescence and quantified the level of expression of two β-catenin/TCF target genes (Ccnd1/Cyclin D1 and Lef1) in colon ACF and carcinomas of Apcmin/+Vdr+/+, Apcmin/+Vdr+/- and Apcmin/+Vdr-/- mice." (PMID 21858154, 2011). "In the nucleus, β-catenin forms functional complexes with transcription factors of the lymphoid enhancer binding factor-1/T-cell factor (TCF) family, activating expression of target genes with cancer-promoting roles." (PMID 19473496, 2009). "Also, it was shown that c-Myc can increase the transcription of WNT-related genes such as lymphoid enhancer-binding factor 1 (LEF1) and augment WNT/β-catenin signaling pathway in cancer cells." (PMID 40141294, 2025). "LEF1 is an activator for the Wnt/β-catenin signaling pathway and EMT for the cancer cell invasion." (PMID 40061926, 2025). "Although it has been extensively studied in the context of cancer and immunology, being considered crucial for early T cell development, research into LEF1 in reproductive medicine, especially regarding endometrial receptivity, has been comparatively scarce." (PMID 39794729, 2025). "Since the inhibitory effect of TLE4 on LEF1 has been previously established, this result further supports the role of miR-362-5p in inhibiting TLE4 expression, thereby promoting cancer progression." (PMID 40406521, 2025). "However, only a few enzymes or metabolites in this pathway are invariably over-expressed across cancers (e.g., NUDT1, LEF1, 9H-xanthine)." (PMID 38723607, 2024). "Moreover, LEF1, RUNX2, CSF1R, VAV3, and FZD3 have been reported to take part in the development of cancer." (PMID 35340229, 2022). "PIK3CA-mutant cancers displayed higher expression of 12 of the 17 Wnt genes compared to PIK3CA wild-type tumors, including five Wnt target genes (LEF1, MYCN, FZD7, SFRP2, and TNFRSF11B) and seven Wnt signaling components (TCF7L1, TCF7L2, CTNNB1, FZD4, SFRP1, WNT5A, and MSX2)." (PMID 34035258, 2021). "It is demonstrated that O'PROTACs of lymphoid enhancer‐binding factor 1 (LEF1) and ETS‐related gene (ERG), two highly cancer‐related transcription factors, successfully promote degradation of these proteins, impede their transcriptional activity, and inhibit cancer cell growth in vitro and in vivo." (PMID 34397171, 2021). "Our previous study also found that LEF1 of the Wnt signaling pathway could directly bind to the promoter of ID1 and promoted cancer stem‐like properties in ESCC." (PMID 33463006, 2021). "Additionally, association analysis of CMTM6 mRNA levels with Wnt target genes (TCF4, LEF1, CD-44, MMP14, ENC1, ID2, PPARA, and JAG1) from the cancer genome atlas HNSCC cohort using GEPIA showed a positive correlation (r > 0.2)." (PMID 33434185, 2021). "LEF1, a downstream mediator of the canonical Wnt pathway, is also considered a promising target due to its involvement in stem-cell maintenance and promotion of EMT phenotype in different cancer types." (PMID 33126517, 2020).
cancer (continued). "LEF1 is a transcription factor that promotes the canonical Wnt/β-catenin signaling pathway by cooperating with TCF4 and is pathologically involved in cancer development and progression in multiple cancer types." (PMID 32933177, 2020). "Moreover, the LEF1/MSC module was specifically activated in LUAD and likely to confer epithelial-to-mesenchymal transition, known important for cancer malignant progression and metastasis." (PMID 29866045, 2018). "The mentioned observations suggest that both sets of genes (LEF1 down-regulated and FOXO4 down-regulated) are actually up-regulated in normal epithelial-mesenchymal transitions, while their expression remains unmodified or decreases in cancer cell lines." (PMID 28798381, 2017). "For example, miR-26b up-regulates the growth hormone levels by targeting lymphoid enhancer binding factor 1 (Lef-1) in GH3 cells, whereas miR-129-5p, miR-202 and two other miRNAs repress the human growth hormone receptor (GHR) expression levels in both normal and cancer cells." (PMID 28402262, 2017). "The LEF-1 transcription factor is expressed in tissues that undergo EMT during embryogenesis, and has been suggested to promote an invasive phenotype in cancer cells." (PMID 28027307, 2016). "Several well-studied cancer-related genes, such as Myc, Rhoa, Lef1 and Rac1, were absent in this pathway of NMR." (PMID 24565050, 2013). "In conclusion, we have shown that the cancer progression effect of BBP is due to its extensive impact on various biological functions, such as activation of proliferation, EMT, and angiogenesis via induction of LEF-1 expression." (PMID 22905168, 2012). "Consistent with this, the expression of cyclin D1 and c-Myc, two down-stream target genes of Wnt signaling that can induce S phase entry in many cancer cell lines, was also decreased under the regulation of the short form of LEF-1 (data not shown)." (PMID 22639890, 2012). "Moreover, LEF1 may contribute to CRC metastasis and drug resistance by enhancing cancer cells' stem cell-like properties." (PMID 40810004, 2025). "Interestingly, we found significantly lower expression of these proteins in DCIS.com cancer cells coimplanted with exp‐CAF 544 cells with LEF1 knockdown compared to those without knockdown." (PMID 39887653, 2025). "The LEF1-targeting O’PROTAC (LEF1 OP-V1) and the ERG-targeting O’PROTAC (ERG OP-C-N1) both employed a VHL E3 ligase ligand, effectively inducing target protein degradation in nanomolar concentrations in the tens and subsequently inhibiting cancer cell growth both in vitro and in vivo." (PMID 40507351, 2025). "Previous studies have shown that ectopic LEF1 expression enhances the expression of epithelial-mesenchymal transition (EMT)-related genes, including the epithelial marker E-cadherin and mesenchymal markers N-cadherin, vimentin, ZEB1, and SNAIL, which are involved in cancer metastasis." (PMID 32933177, 2020). "Additional genes regulated by LEF1 in MYC-transformed cells may be involved in other metabolic and non-metabolic pathways that are important for the deregulated proliferation or other aspects of cancer cell fitness." (PMID 31623618, 2019). "LEF1 expression may contribute to cancer development, but there is a lack of evidence to support malignant phenotype changes, especially motility-associated microstructure changes, such as remodeling of lamellipodia/filopodia based on F-actin/β-tubulin polymerization." (PMID 34639214, 2021). "CFP1 upregulated expression of β-catenin, LEF1, TCF1/TCF7, c-MYC, TGFBR3, and TGFB1, and the cancer-promoting effects of CFP1 were not completely repressed by pathway inhibitors." (PMID 37735441, 2023).
cancer (continued). "We found that the expression levels of the genes in the Wnt/β-catenin signaling pathway, including APC, β-catenin, TCF7L1, TCF7L2, LEF1, MMP7, C-myc, C-jun, CYCLIND1 and GSK-3β, were remarkably higher in cancer than non-cancer tissues in the p.1125Val>Ala mutant FAP family members." (PMID 29050326, 2017).
infection (18 papers, 2013 to 2026). The state of being infected such as from the introduction of a foreign agent such as serum, vaccine, antigenic substance or organism. "In contrast, infection with the vector encoding Lef1 greatly augmented IFN-γ expression in DKK3-treated FoxO4-cKO cells compared with FoxO4-cKO cells under Th1-polarizing conditions, indicating that ectopic Lef1 expression in FoxO4-cKO cells could rescue IFN-γ expression after DKK3 treatment." (PMID 36106640, 2022). "Although Lef1 transcription decreased after infection, it remained higher in Itgae+CD8+ T cells than in Itgae−CD8+ T cells." (PMID 41459157, 2025). "SusceptibleMac specifically upregulated pro-viral factors LEF1 and SOX5, while RepairMac maintained stable transcription factor networks despite infection." (PMID 40723441, 2025). "At the same time, the transcription of genes related to naïve or memory T cells, such as Sell, Il7r, Tcf7, and Lef1, decreased after infection." (PMID 41459157, 2025). "Two to three weeks after infection, the expression of low abundant LEF1 as well as highly expressed CDH1 remained essentially unaffected by GFP-ZBP1." (PMID 23677615, 2013). "Mechanistically, LEF1 expression was significantly downregulated in CD4+ T cells post infection." (PMID 42192546, 2026). "To define the mechanism by which β-catenin transcription is inhibited by SARS-CoV-2, we evaluated the impact of infection on transcription factors known to interact with β-catenin: TCF1, TCF3, TCF4, and LEF1." (PMID 41156605, 2025). "The results indicated that, with the replication of the MDV RB1B strain, the expression level of Wnt/β-catenin signaling pathway-related genes β-catenin, TCF4, LEF1, c-Myc, and Cyclin D1 were significantly downregulated after 24 h of RB1B strain infection and significantly upregulated at 60 h." (PMID 38638910, 2024). "As previously demonstrated, infection causes significant recruitment of SIRT2 to the TSSs of MYLIP, ERRC5, LEF1, SYDE2 and EHHADH but not ARAP2." (PMID 34929015, 2021).
adenocarcinoma (5 papers, 2003 to 2021). A common cancer characterized by the presence of malignant glandular cells. "First of all, our data strongly support a role of LEF1/TCF4 in at least one subgroup of cerebrally metastasized adenocarcinoma patients." (PMID 23224985, 2013). "Recent in vivo experiments in a xenograft brain lung metastasis model postulated a functional role for lymphoid enhancer factor 1/T cell factor 4 (LEF1/TCF4) in a subgroup of adenocarcinomas." (PMID 23224985, 2013). "IHC revealed nuclear TCF4 in all adenocarcinoma samples, whereas only 36 % depicted nuclear LEF1 and nuclear β-catenin signals." (PMID 23224985, 2013). "Nuclear LEF1 immunostaining was detected in 9/25 (36 %) adenocarcinoma brain metastases." (PMID 23224985, 2013). "Gene expression of LEF1 and AXIN2 were correlated in the microarray dataset of the adenocarcinoma brain metastases." (PMID 23224985, 2013). "Their role in humans is still unclear, thus we analyzed LEF1, TCF4, β-catenin, and early stage prognostic markers in 25 adenocarcinoma brain metastases using immunohistochemistry (IHC)." (PMID 23224985, 2013). "This may provide an explanation of the lacking correlation between β-catenin and LEF1 in the adenocarcinomas and the differences in the predictive values of the signatures." (PMID 23224985, 2013).